STAT3 (signal transducer and activator of transcription 3)
Diseases named in the same sentence as STAT3 in open-access papers (continued):
Sharing a sentence is not in itself a finding about the gene and the disease.
cancer (continued). "STAT3 is a secret transcription factor; it is regarded as an appealing target of anti-cancer therapeutics." (PMID 37259360, 2023). "Abnormal STAT3 activation can play a critical role in cancer development by influencing the epithelial–mesenchymal transition (EMT)." (PMID 36672337, 2023). "Alternatively, data have revealed that inhibition of the JAK2/STAT3 signaling pathway results in the downregulation of CSC markers in cancers, which weakens the stemness characteristics of CSCs." (PMID 37853437, 2023). "The signal transducer and activator of transcription 3 (STAT3) is an important target in many types of cancer intervention, including NSCLC, due to its activation in most human cancers." (PMID 37430747, 2023). "Pyrimethamine, a STAT3 inhibitor, has anti-cancer and immune-stimulatory actions in a BC murine model." (PMID 36816749, 2023). "The hyperactivation of STAT3 holds a significant role in the formation of inflammatory tumors within the microenvironment, facilitating both uncontrolled proliferation of cancer cells and metastasis." (PMID 37892997, 2023). "STAT3 is regarded as a therapeutic target in many cancers and regulates cyclinD1, c-Myc, Bcl-2, survivin and ICAM-1, related to cell proliferation, survival, migration, invasion, stemness, immunosuppression and angiogenesis." (PMID 37147297, 2023). "In accordance, several reports demonstrate that drug-induced modulation of STAT3 activation and its target genes prevent muscle wasting mainly in models of cancer cachexia and attenuate denervation induced muscle atrophy and fibrosis." (PMID 37143896, 2023). "Overall, STAT3 is constitutively expressed in cancer cells (only transiently in normal cells) and is involved in the regulation of genes involved in cancer cells’ survival, invasion, angiogenesis and interaction with immune cells." (PMID 36831081, 2023). "After induction of STAT3 signaling by growth factors and cytokines, STAT3 is phosphorylated and translocated to the nucleus to regulate cancer progression." (PMID 37085753, 2023). "This study demonstrated that Pretrichodermamide B is a novel STAT3 inhibitor, which should be considered for further exploration as a promising anti-cancer therapy." (PMID 37073329, 2023). "Studies have shown that knockdown FDPS enhanced apoptosis and ectopic overexpression of FDPS promoted cancer colony growth and proliferation by affecting STAT3, AKT and ERK pathways." (PMID 36634566, 2023). "On the other hand, elevated PGC-1α by LMP1 co-activates with STAT3 to boost PD-L1 expression, consequently facilitating immune escape of cancer cells." (PMID 37803433, 2023). "The expression of p-STAT3 on EP cancer cells after addition of MDSC supernatant is closely similar to the p-STAT3 expression pattern of drug-resistant LP cells, depicting the role of STAT3 in generation of early drug resistance phenotype." (PMID 38304256, 2023). "We used proximity‐dependent labeling to detail mechanistic links between ABI1 and SFKs, STAT3, and NF‐κB and uncover details of involvement of ABI1 in cancer‐linked signaling pathways." (PMID 36635880, 2023). "Especially in mass-type ER-positive cancers, the STAT3 pathway was activated in the canonical pathway analysis, which suggests the increased potential of metastasis in ER-positive cancers." (PMID 37391754, 2023). "Our study confirmed that TROAP was involved in the proliferation and invasion of KIRC and was combined with STAT3 to exert a synergistic effect in promoting cancer, which is expected to be a new therapeutic target for KIRC." (PMID 37298609, 2023). "Some studies have further examined the role of STAT3 as an important link between inflammation and cancer." (PMID 38002302, 2023). "Due to the mechanisms discussed in the previous section, finding or designing agents to inhibit STAT-3 has been a popular strategy among researchers keen on developing therapies against cancer." (PMID 36902456, 2023).
cancer (continued). "We assumed that the regulatory effect of HERC2 on STAT3 signaling participates in the crosstalk between cancer stemness and immune evasion." (PMID 36721234, 2023). "Several natural products (mostly polyphenols and antioxidants) that inhibit STAT-3 have been used in preclinical studies against various types of cancer." (PMID 36902456, 2023). "In the co-culture system, brevilin A abolishes the HSCs-to-CAFs differentiation, inhibits the cancer STAT3 activity and reduces the cancer metastatic potential." (PMID 37062842, 2023). "The association of STAT3 with cancer growth has been documented, and the activation of NLRP3 inflammasome in a cancer microenvironment positively affects cancer growth." (PMID 37047051, 2023). "In particular, the genes responsible for promoting cancer cell proliferation, including Ras, Src, and cyclin D1, serve as direct targets of STAT3." (PMID 37892997, 2023). "This perspective will focus on the complex interplay of NRF2 with STAT3, another transcription factor often aberrantly activated in cancer and driving tumorigenesis as well as immune suppression." (PMID 37000324, 2023). "STAT3 is considered to be an oncogene and has long been a drug target of interest for cancer therapy." (PMID 39872303, 2023). "STAT3 is a transcription factor, and its gene is an oncogene expressed in several human cancers, including pancreatic, having a well-established role in tumorigenesis." (PMID 36495330, 2023). "Although the physiological activation of STAT3 is rapid and transient, dysregulated STAT3 activation is generally found in a broad range of human cancers and is essential to driving malignant transformation and progression." (PMID 37760971, 2023). "The STAT3/NF‐κB pathway is widely documented to stimulate the polarization of M2 macrophages, hence promoting cancer progression." (PMID 37347147, 2023). "It was shown that IL-6 activated gp130 leading to activation of the JAK/STAT pathway and the IL-6/JAK/STAT3 pathway is aberrantly hyperactivated in many types of cancer." (PMID 36911202, 2023). "We also evaluated the effect of STAT3 expression on the prognosis of cancer patients by performing survival analysis, which revealed that, in LGG, the prognosis of OS and PFS in the STAT3 high expression group was worse than that in the low expression group." (PMID 37724127, 2023). "In Lewis cells, suppressing the activities of MMP-2/9 through the modulation of STAT3/MAPK/ERK/JNK signaling pathway significantly inhibited cancer metastasis." (PMID 37766868, 2023). "Prior research further demonstrated that STAT3 activation plays a crucial role in cancer cell proliferation, invasion, and migration, suggesting its potential as a therapeutic target for TNBC treatment." (PMID 38067432, 2023). "The STAT3 inhibitor Stattic significantly reduced sphere formation of cancer stem cells (CSCs) and the expression of OCT4 and SOX2 induced by MDSCs." (PMID 36878933, 2023). "Tip60 interacts with STAT3 and serves as a co-repressor for STAT3 in cancer cells via recruitment of HDAC7 to STAT3 target genes." (PMID 36768434, 2023). "STAT3 can regulate cellular proliferation, invasion, migration, and angiogenesis that are all critical for cancer metastasis, again highlighting the mechanism by which pesticide exposure is capable of modulating metastasis." (PMID 37511154, 2023). "High levels of IL-22 were detected in colonic cancer tissues, where IL-22 exerted pro-tumoral functions by promoting cancer cell activation of STAT-3, reducing tumor cell apoptosis, and increasing the levels of VEGF in the TME." (PMID 37234993, 2023). "The signal transducer and activator of transcription (STAT) proteins, particularly STAT3, are ideal targets for cancer therapy." (PMID 37298475, 2023). "Leptin is known to activate a variety of signalling pathways, in particular the JAK2/STAT3 pathway included in these cancer cells." (PMID 37238197, 2023).
cancer (continued). "In the in vitro anticancer assay, compound NK3 displayed potent antitumor activity against selected cancer cell lines and effectively suppressed nuclear translocation of STAT3." (PMID 37630387, 2023). "Both the survival and expansion of many types of cancer cells depend on the JAK2/STAT3 signaling pathway." (PMID 36852795, 2023). "Extracellular glutamine can act as a signal transducer, activating transcriptional activator 3 (STAT3) to promote cancer cell proliferation." (PMID 37448516, 2023). "Together, these studies demonstrate the complicated and intertwined relationship between (cGAS)/STING activity and STAT3 signaling in cancers with CIN." (PMID 37561163, 2023). "AG490 is a selective inhibitor of JAK2 that inhibits the phosphorylation of STAT3 in various cells including cancer cells." (PMID 37846594, 2023). "Overactivated STAT3 signaling contributes to malignant progression and poor prognosis by promoting the proliferation, survival, metastasis, and invasion of cancer cell, as well as angiogenesis and immune evasion." (PMID 37240202, 2023). "Interleukin 6 (IL-6) acts on cancer cells by inducing the expression of STAT3-dependent genes, thereby promoting cancer cell proliferation and survival." (PMID 37460938, 2023). "STAT3 is a transcription factor that mediates cancer inflammation and promotes cancer cell survival via regulation of various cytokines and growth factors." (PMID 37602328, 2023). "Icariside II showed inhibition of cancer cell apoptosis by inhibition of STAT3 and TLR4-MyD88-ERK signaling in response to these chemotherapeutic agents." (PMID 37743502, 2023). "The Janus kinase (JAK)/signal transducer and activator of transcription 3 (STAT3) regulates the expression of various critical mediators of cancer and is considered as one of the central communication nodes in cell growth and survival." (PMID 37073329, 2023). "JSI-124 has been identified as a selective inhibitor of the JAK2/STAT3 signaling pathway in various types of cancer." (PMID 38001999, 2023). "STAT3 is a classic oncogene that plays a crucial role in promoting the proliferation and metastasis of cancer cells." (PMID 37231451, 2023). "The enhanced expression of cytokines and their receptors mainly result in the aberrant regulation of JAK1/2, STAT1, STAT3, STAT5, and STAT6, causing inflammation and cancer development, cancer recurrence, and decreased overall survival." (PMID 38094755, 2023). "STAT3 signaling pathway is a "bridge" between inflammation and cancer, and is closely related to "inflammation-cancer" transformation." (PMID 37964307, 2023). "Inhibition of STAT3 activation suppressed caspase-3 and proteolysis, leading to an increase in muscle mass in cancer cachexia." (PMID 37217930, 2023). "For example, abnormal activation of IL-6-mediated JAK/STAT3 signal transduction frequently occurs in human cancers and is involved in transformation, tumorigenicity, EMT, and metastasis." (PMID 36911202, 2023). "The inhibition of STAT3 using S3I-201 led to the elimination of both bulk and side population cancer cells in vitro." (PMID 37453969, 2023). "The JAK/STAT3 signal cascade exhibits essential roles in promoting cancer cell survival, proliferation, angiogenesis, and tumor metastasis." (PMID 37333486, 2023). "These insights into the role of the STAT3 signaling pathway in a number of cancer-related cellular events have made this cascade a new potential target for anticancer therapy." (PMID 36675241, 2023). "Our observations have suggested that MDSC secreted IL-10/IL-6/IL-1β are the critical players modulating the drug resistance of cancer cells via STAT3/STAT1/NF-κB pathway." (PMID 38304256, 2023). "STAT3 can enhance cancer stem cell self-renewal and differentiation by altering the gene expression via the epithelial–mesenchymal transition (EMT)." (PMID 37860678, 2023). "STAT3, one of the most activated transcription factors in cancer and gene therapy, has become an important target in malignancy treatment." (PMID 37896137, 2023).
cancer (continued). "In comparison to free STAT3 siRNA and neat curcumin treatment, liposomal delivery of curcumin along with STAT3 siRNA significantly increased inhibition of the growth of cancer cells and apoptotic activities." (PMID 37803407, 2023). "According to several studies, MSC-secreted cytokines influence the IL-6/JAK2/STAT3 signaling pathway in cancer cells, which, in turn, can either stimulate or suppress tumor growth or trigger cancer cell apoptosis." (PMID 38132108, 2023). "STAT3 is responsible for driving transcription of genes, which drive many of the hallmarks of cancer." (PMID 37199043, 2023). "Considering these findings, we used proximity‐dependent labeling (PDL) to detail mechanistic links between ABI1 and SFKs, STAT3, and NF‐κB and uncovered fundamental insight into the role of this adapter protein in cancer." (PMID 36635880, 2023). "We investigated the common genes that contributed to the change in the IL6/JAK/STAT3 and OXPHOS Cancer Hallmark pathways between the GH and SI rats and were reversed by JGT in the SI rats." (PMID 36980301, 2023). "Due to their inhibition of STAT3 signaling, pyrimethamine are being increasingly used in the treatment of human cancer." (PMID 36950551, 2023). "Napabucasin, also named BBI608, is an orally administered STAT3 inhibitor with anti-CSC activity against various types of cancer." (PMID 38140103, 2023). "ERFE is upregulated in cachectic cancer patients' muscle biopsies and in murine cachexia models, where its expression is driven by STAT3." (PMID 38052214, 2023). "p38 MAPK and STAT3 signalling are activated in most of cancer cells and participate in cancer cell proliferation and metastases." (PMID 36419386, 2023). "IL-6 is important inflammatory factor that can activate the STAT3 signaling pathway to induce chemoresistance and radioresistance in a variety of cancer cells." (PMID 36635302, 2023). "The importance of the Stat3 pathway in the interaction between cancer cells and macrophages has been clarified in some previous studies." (PMID 37296952, 2023). "This study evinced a decreased miR-365-3p expression and elaborated on the stimulation of STAT3-mediated discrete signaling pathways and regulation of stemness characters of cancer cells." (PMID 38170015, 2023). "Signal transducer and activator of transcription 3 (STAT3) is ubiquitously hyper-activated in numerous cancers, rendering it an appealing target for therapeutic intervention." (PMID 38023173, 2023). "More specifically, uPAR causes the initiation of activation of other downstream proteins that are known to participate in tissue remodelling and cancer development, leading to the activation of transcription factor STAT3." (PMID 38313431, 2023). "Feedback activation of STAT3 plays a prominent role in mediating resistance to a wide range of targeted cancer therapies and chemotherapy and is considered an important target in anticancer drug resistance treatment." (PMID 37990309, 2023). "In conclusion, with this perspective, we attempted to have shed some light into the complex interplay between NRF2 and STAT3, pathways playing a key role in cancers, either of hematologic and solid origin." (PMID 37000324, 2023). "STAT3 expression is shown to have many downstream effects in macrophages within the TME that increase cancer cell survival." (PMID 37173951, 2023). "Several studies have shown that STAT3 can affect the prognosis of cancer patients by regulating immune microenvironment (IME)." (PMID 37724127, 2023). "An emrging evidence showed that hyperactivation of STAT3 promotes stem cell-like trait in many types of cancers." (PMID 37642779, 2023). "STAT3 activation occurs in most cancers, leading to the expression of various downstream genes responsible for cellular stimulation and influencing cell growth and apoptosis." (PMID 37716993, 2023).
cancer (continued). "STAT3 has been reported to be activated in many cancers, and STAT3 signaling is considered an important process in malignant transformation and angiogenesis induction." (PMID 37298981, 2023). "This is the case with NF-kappa Β and Stat3, found to crosstalk and promote the progression of several cancer types." (PMID 37443838, 2023). "Overexpression of ITGA2 can activate the STAT3 signal pathway and upregulate the expression of PD-L1, thus promoting the invasion of malignant tumors, which are closely related to immunity." (PMID 37907515, 2023). "The anti-cancer effect was observed when the p65 and STAT3 signaling pathways were inhibited, leading to the suppression of malignant behaviors in OSCC cells." (PMID 37833979, 2023). "Although literature data consistently indicate STAT3 as a biomarker predicting poor prognosis of GC, research has poorly investigated its role in cancer treatment efficacy." (PMID 36979673, 2023). "We observed an obvious positive association between the expression level of KDF1 and that of p-STAT3: LUAD cancer cells expressing a high level of KDF1 usually express a high level of p-STAT3 and vice versa." (PMID 38137415, 2023). "Studies have shown that PVT1 participates in multiple signaling pathways in cancer stemness, including the STAT3, PI3K/AKT, YAP1, and TGFβ pathways." (PMID 36894542, 2023). "The JAK-signal transducer and STAT members, particularly STAT3, have been demonstrated to be very important for cancer progression." (PMID 37081086, 2023). "Treatment of EP-cancer cells with MDSC-supernatant significantly upregulated expression of p-STAT3 at 60 mins, which returned to near basal level within 240 mins." (PMID 38304256, 2023). "There are current studies in several cancer types that use STAT3 decoy oligonucleotides as a potential therapeutic for cancers with upregulated STAT3." (PMID 37173951, 2023). "Prior studies have demonstrated a significant involvement of the JAK2/STAT3 pathway in the progression and development of human malignant tumors." (PMID 37766864, 2023). "Similar to inflammatory cytokines, STAT3 had higher levels in the cancer group when compared with the control group (Wilcoxon, p < 0.001)." (PMID 37296861, 2023). "STAT3 participates in cancer initiation by promoting dedifferentiation of acinar cells during pancreatic inflammation." (PMID 36765725, 2023). "Signal transducers and activators of transcription 3 (STAT3) is a hyperactivated oncogene found in various cancers, including GC." (PMID 37894443, 2023). "The expression of signal transducer and activator of transcription 3 (STAT3) in human cancer cells changes, and during cancer progression, the expression tends to increase." (PMID 37085753, 2023). "Inhibition of STAT3 was identified as a meaningful strategy to overcome acquired cancer drug resistance." (PMID 37514107, 2023). "Suppression of STAT3 expression reduced cancer progression, while curcumin also exhibited anticancer activity." (PMID 38140019, 2023). "The IL‐6/JAK/STAT3 signaling pathway is frequently overactivated in various cancer types, and its dysregulation is commonly correlated with unfavorable clinical outcomes." (PMID 38125769, 2023). "This was accompanied by decreased activity of specific signalling pathways (STAT3, NF-κB, and C/EBPβ) involved in cancer growth." (PMID 37221596, 2023). "Mechanistically, the anti-cancer effects of DDX58 were achieved by interacting with STAT3 and inhibiting the STAT3/CSE signaling." (PMID 38023215, 2023). "The signaling transducer and activator of transcription 3 (STAT3) are activated in various types of cancer and are related to cell proliferation, migration, and invasion." (PMID 36978836, 2023). "Phosphorylated STAT3 (pSTAT3) was detected in the nuclei of cancer cells, and a higher positive signal was observed in the peripheral area than in the central area of the cancer nest, which is consistent with our previous study." (PMID 36961655, 2023).